MTOR (mechanistic target of rapamycin kinase)
Diseases named in the same sentence as MTOR in open-access papers (continued):
Sharing a sentence is not in itself a finding about the gene and the disease.
renal cell carcinoma (continued). "For example, temsirolimus and everolimus, inhibitors of the mTOR signaling pathway which governs protein synthesis, have been approved for the treatment of renal cell carcinoma." (PMID 30453531, 2018). "By using this strategy, we identified temsirolimus, a mTOR inhibitor approved for renal cell carcinoma, as a potential therapeutic agent for the treatment of lung tumor." (PMID 30087612, 2018). "Previous reports have demonstrated that silibinin inhibits mTOR pathway in both renal cell carcinoma and multiple myeloma cells." (PMID 29780826, 2018). "The mechanistic target of rapamycin (mTOR) is an established therapeutic target in renal cell carcinoma (RCC)." (PMID 30256787, 2018). "MTOR inhibitors are used predominantly to treat renal cell cancers and neuroendocrine tumours, and as anti-rejection agents in solid organ transplantation." (PMID 30326612, 2018). "Patients with renal cell carcinoma experienced prolonged disease stabilization under co-administration of the mTOR inhibitor ridaforolimus and the HDAC inhibitor vorinostat in a phase I study." (PMID 29299126, 2017). "Particularly, renal cell carcinoma (RCC) were associated with fewer rate of mucositis (RR 1) than astrocytoma (RR 5.29), gastric cancer or breast cancer, regardless the combination of mTOR-inhibitors with other drugs." (PMID 28642709, 2017). "Seven were on mTOR inhibitors before cancer and 2 had graft nephrectomy (one due to renal cell carcinoma and the other due to non-Hodgkin lymphoma within the grafts) with subsequent withdrawal of immunosuppression." (PMID 28160552, 2017). "There are 9 pathways related to MS, containing fructose and mannose metabolism, glycosaminoglycan degradation, proteasome, ErbB signaling pathway, mTOR signaling pathway, Alzheimer’s disease, Parkinson’s disease, Huntington’s disease and renal cell carcinoma." (PMID 29312536, 2017). "Mammalian target of rapamycin (mTOR)in renal cell carcinoma (RCC) represents a valuable oncotarget for treatment." (PMID 28257457, 2017). "Although the mechanistic target of rapamycin (mTOR) inhibitor, everolimus, has improved the outcome of patients with renal cell carcinoma (RCC), improvement is temporary due to the development of drug resistance." (PMID 27863441, 2016). "There was a recent report of renal cell carcinoma patients with extended benefit from mTOR inhibitor showed that TSC1 and TSC2 offer explanation for treatment response." (PMID 26859683, 2016). "Inhibitors of the mTOR pathway have in fact shown clear benefits in some cancers such as Mantle Cell Lymphomas, Renal Cell Carcinoma and Tuberous Sclerosis Complex-related tumors but have limited efficacy as single agents in most other cancers." (PMID 26824423, 2016). "In one of these three possible renal cell carcinomas (case P0039), copy loss of TSC1 and a likely loss-of-function deletion in NF2 were detected, strongly suggesting AKT/mTOR pathway was activated." (PMID 27245685, 2016). "Inhibitors of the mTOR pathway, such as everolimus, are promising compounds to treat patients with renal cell carcinomas (RCCs)." (PMID 26506236, 2016). "With the development of multiple anti-VEGF (vascular endothelial growth factor) agents and mTOR (mammalian target of rapamycin) inhibitors, we have seen significant progress over the last few years in targeted therapies for treating renal cell carcinoma (RCC)." (PMID 25734007, 2015). "In renal cell carcinoma cells, mTOR signaling increased the reduction of nuclear p27 protein levels." (PMID 26500453, 2015). "Everolimus (RAD001) is an orally administered mTOR inhibitor that is well known for its antitumor efficacy and that has been approved for the treatment of several solid tumors, including renal cell carcinoma." (PMID 25886409, 2015).
renal cell carcinoma (continued). "For example, we and others have shown that mTOR inhibition attenuates chemotherapy-mediated cell death in colon and renal cell carcinoma cell lines, and in certain genetic contexts, such as loss of TSC1/2 or REDD1." (PMID 25460505, 2015). "The relevance of mTOR signalling in Renal Cell Carcinoma (RCC) is highlighted by the success in using mTOR inhibitors (temsirolimus and everolimus) to treat patients with advanced disease." (PMID 26097872, 2015). "Inhibitors of mammalian targets of rapamycin (mTOR) or vascular endothelial growth factor receptor (VEGFR) will be applied clinically for the treatment of renal cell carcinomas with the aim of depriving the cells of nutrition." (PMID 24796485, 2014). "DDIT4 encodes DNA damage-inducible transcript 4, also known as REDD1, which is a negative regulator of mammalian target of rapamycin (mTOR) and a possible tumor suppressor in renal cell carcinoma." (PMID 24498386, 2014). "In 2007, temsirolimus was the first MTOR inhibitor to be approved by the FDA for the treatment of advanced-stage renal cell carcinoma." (PMID 25375091, 2014). "The mTOR pathway is a major cancer drug target and renal cell carcinoma is one cancer that has demonstrated clinical success with rapalog therapy." (PMID 24136229, 2013). "In particular, the anti mTOR therapies are an emerging strategy for renal cell carcinomas and breast cancer treatment." (PMID 24958265, 2013). "The oral mTOR (mammalian target of rapamycin) inhibitor, everolimus, affects tumor growth by targeting cellular metabolic proliferation pathways and delays renal cell carcinoma (RCC) progression 1–2." (PMID 24156027, 2013). "In this work, we evaluate the anti-tumor activity of two novel IGF-1R-targeting agents against renal cell carcinoma given alone or in combination with an mTOR inhibitor." (PMID 23548153, 2013). "The mTOR (mammalian target of rapamycin) inhibitor, everolimus, affects tumor growth by targeting cellular metabolic proliferation pathways and delays renal cell carcinoma (RCC) progression." (PMID 24156027, 2013). "Here we show that autophagy is a resistance mechanism of human renal cell carcinoma (RCC) cell lines to mTOR inhibitors." (PMID 22848625, 2012). "The prototype mTOR inhibitor, sirolimus, has long been utilized as an antirejection drug following solid organ transplant, and mTOR inhibitors have recently been investigated in clinical trials for treating malignancies, such as renal cell carcinoma." (PMID 23125857, 2012). "In other tumors where mTOR plays an important role, including renal cell carcinomas, a mechanism by which metformin inhibits tumorigenicity via mTOR and activation of AMPK has been demonstrated." (PMID 22203527, 2011). "Reduction in tumor burden has been previously demonstrated in a PCa xenograft model treated with concurrent HDAC/mTOR inhibition and more recently in renal cell carcinoma (RCC) xenograft models." (PMID 22087262, 2011). "Everolimus is a once-daily, oral inhibitor of mTOR (mammalian target of rapamycin) indicated for the treatment of advanced renal cell carcinoma in patients, whose disease has progressed on or after treatment with VEGF-targeted therapy." (PMID 21584218, 2010). "The mammalian target of rapamycin (mTOR) is an important therapeutic target in the treatment of renal cell carcinoma (RCC)." (PMID 20823888, 2010). "mTOR inhibitors gain much clinical interest as an antitumoural agent, such as in renal cell carcinoma." (PMID 19240722, 2009). "Temsirolimus is the first-in-class mammalian target of rapamycin (mTOR) inhibitor that was approved for the treatment of patients with advanced poor prognosis renal cell carcinoma." (PMID 18797463, 2008). "TKIs and mTOR inhibitors are typically first-line drugs for the treatment of renal cell carcinoma." (PMID 41013841, 2025).
renal cell carcinoma (continued). "For instance, epidermal growth factor receptor (EGFR) or mitogen-activated protein kinase (MEK1/2) kinase activity hinders the growth of renal cell carcinoma cells and enhances the growth inhibitory effects of the mammalian target of rapamycin (mTOR) inhibitor rapamycin." (PMID 41340127, 2025). "Studies in patients with renal cell carcinoma have shown that mutations in TSC1/2 and mTOR are associated with rapalog resistance, although these mutations are not present in most patients, supporting the potential of targeting Ephexin1 in overcoming resistance." (PMID 40855114, 2025). "Furthermore, the combination of mTOR and other upstream inhibitors has demonstrated significant potential for the treatment of renal cell carcinoma." (PMID 41340127, 2025). "Moreover, gypenoside reportedly promoted cell apoptosis via the PI3K/AKT/mTOR signaling pathway in renal cell carcinoma and bladder cancer cells." (PMID 38482051, 2024). "Interestingly, mouse modeling studies showed that mTOR activation in combination with inactivation of the p38MAPK initiates renal cell carcinoma." (PMID 38318383, 2024). "Activation of the PI3K/Akt/mTOR pathway is involved in renal cell carcinoma resistance." (PMID 39075562, 2024). "Also, by inhibiting the PI3K/Akt/mTOR signaling pathway, bufalin inhibits renal cell carcinoma proliferation and metastasis." (PMID 37065178, 2023). "The activated mTOR signaling pathway was related to the development of renal cell carcinoma." (PMID 37198626, 2023). "In renal cell carcinoma, an mTOR inhibitor has been demonstrated to promote autophagy-mediated RIPK clearance to inhibit necroptosis, but it also exerts a positive role in necroptosis by suppressing Nrf2 nuclear translocation and consequent antioxidant defense." (PMID 38164133, 2023). "Additionally, PI3K/Akt/mTOR signaling is dysregulated in renal cell carcinomas (RCCs), and mTOR inhibitors such as temsirolimus and everolimus are important therapeutic options for RCC treatment." (PMID 37237486, 2023). "The PI3K/AKT/mTOR pathway has been found to be abnormally active in renal cell cancer." (PMID 37752545, 2023). "Therefore, autophagy inhibitors are expected to enhance the efficacy of mTOR inhibitors in treating renal cell cancer." (PMID 38164133, 2023). "In addition to upregulation of VEGF and HIF secondary to inactivation of the VHL gene, activation of the mammalian target of rapamycin (mTOR) pathway also leads to increased expression of HIF-1 and was implicated as a valid target in renal cell carcinoma." (PMID 35326557, 2022). "The mTOR pathway was considered to play a central role in cell growth and metabolism regulating in renal cell carcinomas oncogenesis and the activation of mTOR results in the downregulation of fumarase and fumarate accumulation in Tsc1-deficient animals and cells." (PMID 35163394, 2022). "In clear cell renal cell carcinoma, PTPN3 and PTPN13 act as tumor suppressors by inactivating the AKT signaling pathway, whereas PTPN12 restrains the proliferation of renal cell carcinoma by inhibiting PI3K/mechanistic target of rapamycin (mTOR) pathway activity." (PMID 35957898, 2022). "In addition, temsirolimus, an mTOR drug that has exhibited the potential to reduce the size of endometrial lesions in vitro and in vivo, is currently approved for the treatment of renal cell carcinoma." (PMID 35052675, 2022). "In the renal cell carcinoma xenografted mouse model, the combination of mTOR inhibitors with PD-L1 blockade could enhance the therapeutic efficacy of tumor suppression." (PMID 35201501, 2022). "Notably, both mTORC1 and mTORC2 are critical to the development of renal cell carcinoma, and mTOR drug inhibitors have shown therapeutic value for RCC." (PMID 35614940, 2022). "Finally, inhibition of AKT/mTOR using NVP-BEZ235 was efficacious in reducing tumor burden in a 786-0 xenograft model of renal cell carcinoma." (PMID 34002003, 2021).
renal cell carcinoma (continued). "Use of curcumin to target AKT/mTOR pathway could be an effective treatment alternative for renal cell carcinoma." (PMID 34402718, 2021). "Additionally, vascular-endothelial growth factor (VEGF) and mammalian target of rapamycin (mTOR) inhibitors supersede for treatment of renal cell carcinoma." (PMID 34555656, 2021). "The results indicated that high METTL3 expression was associated with some essential signaling pathways including ERBB pathway, MAPK pathway, mTOR pathway, renal cell carcinoma, pathway in cancer, TGF-β pathway and Wnt pathway, giving a clue of the underlying mechanism in the pathogenesis of ccRCC." (PMID 33430867, 2021). "Additionally, suppression of the Akt/mTOR signaling pathway by PL in renal cell carcinoma cells was demonstrated to be reactive oxygen species (ROS) dependent, which led to cell death and inhibition of tumor initiation and progression." (PMID 36046754, 2021). "In vitro, thymoquinone in renal cell cancer lines (ACHN &786‐O) of xenograft model markedly suppressed the metastatic capacity through AMPK/mTOR signaling pathway, inhibited the migration and invasion, induced autophagy, and suppressed the EMT dose‐dependently." (PMID 33747489, 2021). "Activation of the PI3K/AKT/mTOR pathway promotes the progression of renal cell carcinoma (RCC)." (PMID 33051401, 2020). "This analysis led to the identification of temsirolimus, a U.S. Food and Drug Administration (FDA)-approved mTOR inhibitor for renal cell carcinoma, which was repositioned from both stages of lung tumor cells and was tested in combination with thoracic radiation in NSCLC." (PMID 30087612, 2018). "On May 30, 2007, the U. S. Food and Drug Administration granted approval for temsirolimus, an mTOR inhibitor, for the treatment of advanced renal cell carcinoma." (PMID 30245856, 2018). "Most of these pathways involve in the body’s nerves regulating and regulation, in which six are confirmed MS-related by literatures, including the proteasome, mTOR signaling pathway, Alzheimer’s disease, Parkinson’s disease, Huntington’s disease and renal cell carcinoma pathway." (PMID 29312536, 2017). "mTOR-inhibitors, such as everolimus, are currently being used in the management of a number of solid tumors including breast, neuroendocrine of the GI tract and renal cell cancers." (PMID 28642709, 2017). "EAAT3 may be effective in the treatment of advanced renal cell carcinoma by regulating the mTOR pathway as effectively as temsirolimus and everolimus, which are kinase inhibitors of mTOR complex 1 (mTORC1)." (PMID 27231847, 2016). "VEGFC is involved in two signaling pathways: renal cell carcinoma and mTOR." (PMID 26571238, 2015). "Our studies showed that temsirolimus, an inhibitor of mTOR, reduced cancer cell growth slightly, but did not cause cell death against the “resistant” type of renal cell carcinomas under glucose deprivation." (PMID 24796485, 2014). "Everolimus (40-O-(2-hydroxyethyl)-rapamycin, RAD001/Afinitor®) is an orally bioavailable inhibitor of the mammalian target of rapamycin (mTOR) which is currently approved for the treatment of advanced renal cell carcinoma and progressive neuroendocrine tumors of pancreatic origin (PNET)." (PMID 23520486, 2013). "Moreover, metformin has been reported to inhibit the tumor progression of renal cells carcinoma by inhibiting mTOR activity through AMPK modulation." (PMID 24958265, 2013). "The mTOR signaling pathway plays a crucial role in the carcinogenesis of renal cell cancer (RCC)." (PMID 23209702, 2012). "The proof of principle that a drug targeting mTOR can improve survival has been obtained recently from a large randomised trial using temsirolimus as a first-line therapy in patients with advanced poor prognostic renal cell carcinoma." (PMID 18797463, 2008).
renal cell carcinoma (continued). "The observed clinical efficacy of mTORC1 inhibitors in patients with renal cell carcinoma may be mediated in part by dependence of efficient HIF translation on the mTOR pathway by intercepting the VEGF/VEGFR and/or PDGF/PDGFR signalling cascades." (PMID 18797463, 2008). "In renal cell carcinoma (RCC) models, the combination of the mTOR inhibitor Everolimus and the Survivin inhibitor YM155 (EY-L) significantly potentiates radiosensitization." (PMID 40725100, 2025). "TFEB has been shown to mediate resistance to mTOR inhibition in renal cell carcinoma (RCC) and to increase programmed death ligand-1 (PD-L1) expression in cancer cells, thereby promoting immune evasion." (PMID 39624081, 2024). "Moreover, it was reported that the mammalian target of rapamycin (mTOR) activation is important for the betulin‐induced cytotoxicity in renal cell carcinoma, as mTOR increased pyruvate kinase muscle isozyme M2PKM2 and hexokinase 2 (HK2) expression by upregulating the aerobic glycolysis." (PMID 39723067, 2024). "Temsirolimus is an antineoplastic agent employed in the treatment of renal cell carcinoma (RCC), applying its therapeutic effects through mTOR inhibition." (PMID 37513921, 2023). "The results showed that cell cycle, mismatch repair, DNA replication, nucleotide excision repair, renal cell carcinoma, mTOR signaling pathway were enriched in the NR1H4 highly expressed group, which provides a potential mechanism whereby NR1H4 might regulate the progression of ccRCC." (PMID 36123627, 2022). "Besides, TFEB could elevate PD-L1 expressions to promote immune evasion resistance to mTOR inhibition in renal cell carcinoma, highlighting the significant relationships between TFEB and immunotherapy." (PMID 35773729, 2022). "Although the effects of METTL3 are mechanistically similar to those in GC and LCA in terms of the EMT and PI3K-Akt-mTOR pathways, in renal cell carcinoma (RCC), knocking down METTL3 significantly promoted cell proliferation, migration and invasion." (PMID 33431045, 2021). "However, the clinical role of mTOR in renal cell carcinoma (RCC) is controversial." (PMID 34458019, 2021). "In renal cell carcinoma, treatment with simvastatin, an inhibitor of HMG-CoA reductase, and bufalin suppressed the metastatic activity of RCC cells that was accompanied by inhibition of the Akt/mTOR pathway." (PMID 32235551, 2020). "Clinical studies have demonstrated a significant benefit of the mTOR inhibitors temsirolimus (Torisel®; Wyeth Pharmaceuticals Inc., Philadelphia, PA, USA) and everolimus (Afinitor®; Novartis Pharmaceuticals Corporation, East Hanover, NJ, USA) in treating renal cell carcinoma (RCC) patients." (PMID 31010254, 2019). "Interestingly non-recurrent mTOR mutations scattered over the C-terminus have been reported in renal cell carcinoma." (PMID 31258848, 2019). "mTOR signalling is commonly activated in cancer which has led to the generation of a number of mTORC1 inhibitors (rapalogs) that have demonstrated clinical efficacy in a subset of cancers including relapsed renal cell carcinoma and postmenopausal hormone-receptor-positive breast cancer." (PMID 25460505, 2015). "mTOR inhibitors are used to treat metastatic renal cell cancer (RCC), but most patients eventually become resistant." (PMID 26134285, 2015). "In this report, we describe the case of a patient with TSC in whom TSC-related symptoms improved and a partial response to recurrent renal cell carcinoma (RCC) was achieved after treatment with the mTOR inhibitor everolimus." (PMID 24612911, 2014). "Rapamycin derivatives allosterically targeting mTOR are currently FDA approved to treat advanced renal cell carcinoma (RCC), and catalytic inhibitors of mTOR/PI3K are now in clinical trials for treating various solid tumors." (PMID 25180793, 2014).